INS (insulin)
Diseases named in the same sentence as INS in open-access papers (continued):
Sharing a sentence is not in itself a finding about the gene and the disease.
type 2 diabetes (continued). "People with type 1 require insulin injections to prevent life-threatening diabetic ketoacidosis, whereas people with type 2 diabetes can treat their high blood glucose with diet or tablets." (PMID 32607451, 2020). "The sensitivity of insulin treatment to predict type 1 diabetes was 90.5% and specificity 64.7% (AUC 0.78) according to the ROC analyses; sensitivity as regards predicting type 2 diabetes was 56.9%, and specificity 74.6% (AUC 0.66)." (PMID 32725280, 2020). "Taken together, our data strongly suggest GN as a potential activator of insulin signaling upon exposure to a diet prone to obesity, thus posing it as an attractive drug candidate targeting type 2 diabetes." (PMID 33003580, 2020). "In fact, the presence of soluble and insoluble NSPs has been shown to reduce FBG and HbA1c and increase insulin sensitivity among patients with type 2 diabetes." (PMID 33281534, 2020). "In another study, the hypoglycemic and hypolipidemic effects of CRCs were evaluated in streptozotocin-induced type II diabetes rats, where advanced glycation products, glucose and HbA1c levels, and fasting insulin levels were measured." (PMID 33182581, 2020). "In the laboratory, signals that trigger inflammation and molecules called fatty acids can mimic type 1 or type 2 diabetes respectively when applied to insulin-producing cells." (PMID 33164744, 2020). "Other risk factors, such as type 2 diabetes mellitus (T2DM), seem to have a bidirectional relationship with AD, because it involves modifications in vascular function and structure, glucose metabolism, and insulin signaling, thus contributing to neurodegeneration." (PMID 33126696, 2020). "APN has been shown to enhance insulin sensitivity and protect against obesity, type 2 diabetes and atherosclerosis." (PMID 32152335, 2020). "This attribute facilitates the use of U-500R as insulin monotherapy, which was tested and shown to significantly improve HbA1c in patients with type 2 diabetes inadequately controlled on high doses of U-100R therapy (> 200 units/day)." (PMID 32396624, 2020). "In this study, we used the high-fat diet and STZ-induced rat model of type 2 diabetes to examine the effect of magnesium supplementation on insulin sensitivity." (PMID 32952944, 2020). "In studies in type 2 diabetes, subjects needed an average of 12% more U-300 than U-100 insulin glargine for the same glycemic effect." (PMID 32396624, 2020). "People with type 2 diabetes develop the disease when β-cells become exhausted from increased insulin demand and stop producing insulin." (PMID 33164744, 2020). "Type 2 diabetes is a form of chronic diabetes triggered by hyperglycemia, and it leads to impaired insulin secretion, insulin action or both." (PMID 32957510, 2020). "Obesity is one of the main menaces of type 2 diabetes, which generally results in impaired insulin action, and most patients in this case are obese." (PMID 33228164, 2020). "Accordingly, several human and animal studies have demonstrated that exogenous Cr administration improves glucose tolerance and insulin sensitivity in type 2 diabetes and obesity." (PMID 32961883, 2020). "A phase I clinical trial (NCT00982254) compared the efficacy of oral insulin/SNAC and subcutaneous injection of regular human insulin for the treatment of type 2 diabetes." (PMID 33352795, 2020). "This hepatokine is a liver-derived protein and, together with free fatty acids, induces apoptotic signals in the beta islet cells of the pancreas, reducing the secretion of insulin and further exacerbating diabetes type 2." (PMID 33182564, 2020). "Pioglitazone-HCl (PGZ) is a member of the thiazolidinediones and is used to treat type 2 diabetes mellitus (T2DM) due to its efficacy in glycemic control by acting as an insulin sensitizer." (PMID 32178278, 2020).
type 2 diabetes (continued). "Controlled studies of isoenergetic TRE have shown beneficial effects on glucose tolerance, insulin sensitivity, and 24-h glucose profiles in individuals at risk of developing type 2 diabetes mellitus (T2D) as well as reductions in appetite in persons with overweight/obesity." (PMID 33105701, 2020). "This burden leads to people with type-II diabetes being opposed to subcutaneous insulin and to cease use of subcutaneous insulin to control their blood glucose levels." (PMID 32785196, 2020). "The present project showed that RHI was inversely associated with incident type 2 diabetes as well as HOMA-IR and fasting insulin levels at follow-up in participants who were normoglycemic at baseline." (PMID 32690629, 2020). "In several models of obese type-2 diabetes, oxidation of fatty acids in β-cells is enhanced along with reduced glucose-stimulated insulin secretion, favoring detoxification of intracellular lipids." (PMID 33198243, 2020). "The mean time to insulin initiation in the overall type 2 diabetes population was >8 years across all waves and remained stable over time." (PMID 31901950, 2020). "We investigated the associations of metformin, statin, ACE inhibitor/angiotensin II receptor blocker (ARB), sulfonylurea (SU) derivatives and insulin use with the total plasma N-glycome in type 2 diabetes." (PMID 32616483, 2020). "Accordingly, the impaired action of insulin in type 2 diabetes leads to reduced plasma triglyceride clearance, which in turn contributes to elevated post-prandial lipid excursions and fasting dyslipidemia." (PMID 32504883, 2020). "Sitagliptin is dipeptidyl peptidase-4 (DPP-4) inhibitor, is used to treat diabetes mellitus type II as it increases the production of insulin and decreasing the production of glucagon by the pancreas." (PMID 32298346, 2020). "A decreased proportion of type I fibres has been found in various insulin resistant states such as the metabolic syndrome, obesity and in some patients with type 2 diabetes." (PMID 31668722, 2020). "Metformin has been extensively used since the 1950s, as the first-line treatment against Type II diabetes and is one of the most commonly prescribed drugs in the world, either as a monotherapy or in combination with insulin or other anti-hyperglycemic agents." (PMID 33071237, 2020). "In ESTRID, individuals with LADA were younger and leaner, more likely to be treated with insulin, had lower insulin secretion, and were less insulin resistant than those with type 2 diabetes." (PMID 32835373, 2020). "Lipohypertrophy remains a frequent complication of insulin therapy, reportedly in 28.7% of those with type 1 diabetes and 3.6% with type 2 diabetes with a greater tendency of developing the lesion in patients using medium or long-acting insulin." (PMID 32056035, 2020). "Most medications for type 2 diabetes are synthetic drugs orally taken, but the frequent insulin injection is essential for type 1 diabetes to survive." (PMID 32148550, 2020). "The glucagon pathway is suspected of being the target of BBR beyond the insulin pathway because abnormally elevated glucagon levels and increased hepatic glucagon sensitivity drive hepatic gluconeogenesis in type 2 diabetic patients." (PMID 31976031, 2020). "Basal insulin, available in intermediate-acting and long-acting formulations, is often the first insulin used in treating people with type 2 diabetes." (PMID 32396624, 2020). "Type 2 diabetes (formerly named non-insulin-dependent) results from the body's inability to respond properly to the action of insulin produced by the pancreas." (PMID 33294218, 2020). "Exogenous insulin is mainly used in patients with type 1 diabetes and type 2 diabetes poorly controlled with diet and oral anti-diabetic drug (OAD)." (PMID 33167951, 2020). "Insulin treatment is necessary for many patients with type 2 diabetes, and its delivery must be safe and comfortable." (PMID 33086494, 2020).
type 2 diabetes (continued). "The anthocyanin treatment was compared to glibenclamide, a reference sulfonylurea for the pharmaceutical management of type-2 diabetes, which promotes hypoglycemia via the stimulation of insulin secretion." (PMID 33233708, 2020). "Early postprandial peaks in insulin secretion, proportional to glucose, have been observed in patients with Type 2 diabetes undergoing RYGB, that correlated with improved hemoglobin A1C." (PMID 32687546, 2020). "Physical inactivity-associated low skeletal muscle mitochondrial oxidative capacity is suggested to contribute to skeletal muscle fat accumulation and insulin resistance and thereby is thought to be involved in the development of type 2 diabetes." (PMID 32185462, 2020). "For example, NAFLD liver fat score including the presence of the metabolic syndrome and type 2 diabetes, fasting serum insulin, AST, and the AST/ALT ratio, had an AUC of 0.86 in the validation group." (PMID 32714888, 2020). "In epidemiological studies of type 2 diabetes, it has been consistently observed that the addition of insulin to the treatment regimen or the intensification of insulin treatment result in a higher rate of cardiovascular events." (PMID 32819363, 2020). "Intravenous insulin treatment had strong beneficial effects on inflammation and coagulation in hospitalized type 2 diabetic patients with COVID-19 over a period of 2 weeks." (PMID 33584268, 2020). "Type 2 Diabetes is a chronic metabolic disorder described by reduced insulin secretion and insulin action and hypergycemia." (PMID 33101408, 2020). "Cold acclimation and exercise training were previously shown to increase peripheral insulin sensitivity in human volunteers with type 2 diabetes." (PMID 32887608, 2020). "Stimulated glucose and insulin concentrations are frequently used to determine pharmacologic type 2 diabetes treatment outcomes, yet marked intra-individual variability in OGTT results across repeated tests is well-established." (PMID 35601187, 2020). "Accordingly, SCGN was recently found to be elevated in patients with type 2 diabetes and has been related to beta-cell proliferation and insulin secretion." (PMID 32708966, 2020). "Similar results were reported in studies on type 2 diabetes patients and on pregnant women in Austria, though in these cases, poorer QoL was only found at the beginning of insulin therapy." (PMID 33008418, 2020). "In people with type 2 diabetes, the pancreas can be sluggish about secreting insulin in response to a meal, leading to postprandial hyperglycemia." (PMID 32471238, 2020). "Oleuropein also prevents palmitic acid-induced myocellular insulin resistance, suggesting the possibility for this molecule to be active for type 2 diabetes by decreasing insulin levels at muscular level." (PMID 33238414, 2020). "An important aspect of this burden is the co-occurrence of disorders of glucose and insulin homeostasis (DGIH) [type-2 diabetes mellitus (T2DM) and prediabetes] and obesity." (PMID 30854996, 2020). "In individuals with type 2 diabetes, casein hydrolysate (12 g) acutely increases the postprandial insulin response." (PMID 33322540, 2020). "In this study, insulin-naive adults with type 2 diabetes treated with human vs analogue insulin had similar rates of major cardiovascular events, mortality due to cardiovascular disease, and overall mortality." (PMID 31977057, 2020). "On the other hand, insulin secretion is severely impaired in poorly controlled type 2 diabetes which leads to the lower concentration of the serum insulin." (PMID 32509880, 2020). "Patients with long-standing type 2 diabetes and obesity on IT can, with sufficient weight loss achieved through a low-energy TDR intervention, reduce insulin burden and improve QoL." (PMID 32049634, 2020).
type 2 diabetes (continued). "This study evaluated patients’ safety and comfort when using a Gensulin® delivery device, GensuPen (Bioton), a reusable insulin pen device for injecting Gensulin® insulin among adult and elderly patients with type 2 diabetes." (PMID 33086494, 2020). "The strengths of this study were that it was the first and the longest study that compared post-meal walking with prandial insulin in basal insulin treated type 2 diabetic patients with valid study design." (PMID 32236116, 2020). "Together, these inflammatory cytokines and chemokines activate intracellular pathways that promote insulin-resistance and, ultimately, type-2 diabetes." (PMID 32153503, 2020). "Among obese men with Type 2 diabetes, who underwent 10-week caloric restriction, a significant decrease in body weight, fat mass, and fat-free mass, as well as fasting glucose and insulin were observed." (PMID 33042834, 2020). "Type 2 diabetes mellitus (T2D) is a metabolic disease characterized by raised fasting glucose levels due to insulin resistance and impaired insulin production." (PMID 33020500, 2020). "In type 2 diabetic KKAy mice, 19 leads to a pronounced and dose-dependent improvement of hyperglycemia and insulin secretion." (PMID 33776749, 2020). "As shift workers have a higher incidence of obesity and type 2 diabetes, these epidemiological data implicate diurnal insulin patterns in disease." (PMID 31918914, 2020). "In the present study, the highest fasting insulin, HOMA-IR and risk of type 2 diabetes was observed among individuals with a very high number of AMY1 copies (10 copies or above) having the lowest starch intake." (PMID 33490099, 2020). "Short-term intensive insulin therapy induces long-term glycemic remission in half of patients with newly diagnosed type 2 diabetes." (PMID 32149152, 2020). "Six of these pathways including PI3K-Akt signaling pathway, cAMP signaling pathway, NAFLD, type II diabetes mellitus, and insulin secretion are directly related to carbohydrate, lipid, and energy metabolism." (PMID 32408171, 2020). "The incretin effect is responsible for 50-70% of total insulin secretion after glucose ingestion and is often reduced in patients with type 2 diabetes mellitus (T2DM)." (PMID 32742592, 2020). "The protective effects of fruit and vegetables intake toward type 2 diabetes mainly depend on their rich fiber content, that improves insulin sensitivity." (PMID 32046004, 2020). "The management of patients with long-standing type 2 diabetes and obesity receiving insulin therapy (IT) is a substantial clinical challenge." (PMID 32049634, 2020). "Another study found that piperine reduces blood glucose levels as well as improving the sensitivity of insulin intake in type 2 diabetes." (PMID 32650482, 2020). "Both type 1 and type 2 diabetes comprise abnormalities of insulin action, which includes insulin insensitivity and resistance." (PMID 31953455, 2020). "The AT+RT intervention resulted in the greatest improvements in blood glucose, plasma lipids and fasting insulin in patients with and animal models of type 2 diabetes." (PMID 31900223, 2020). "The use of medications for the treatment of Type 2 diabetes other than metformin and insulin increased from 22.3% (20.5%–24.2%) to 27.3% (26.0%–28.6%) (p < 0.001)." (PMID 33692751, 2020). "Thiazolidinediones are an important class of insulin sensitizers used in the treatment of type 2 diabetes." (PMID 33312199, 2020). "In type 2 diabetes, muscle and fat cells are “resistant” to the actions of insulin and compensatory mechanisms are activated in the β-cell to secrete more insulin." (PMID 32636751, 2020). "Through feeding of the high-starch or high-sucrose diets, the ExHC rats developed a type-2-diabetes-like status, high plasma insulin levels, and high HOMA-IR." (PMID 32163433, 2020).
type 2 diabetes (continued). "This study provided the first evidence that L. paracasei HII01 administration ameliorates hyperglycemia and enhances insulin stimulated glucose uptake in HFD–STZ induced type 2 diabetic rats." (PMID 33019697, 2020). "Elevated plasma glucose and plasma insulin concentration though seen in a prediabetic state, have been found to have similar results in type 2 diabetic patients with a heightened HPA axis activity." (PMID 33308255, 2020). "Similar to the analysis results where psychiatric diagnoses were outcome variables, offspring of severely obese mothers with insulin-treated pregestational diabetes or type 2 diabetes had the highest effect size on psychotropic medication purchase." (PMID 32031649, 2020). "Initiation of insulin therapy for the management of type 2 diabetes can be an unwelcome and distressful development for patients." (PMID 32406854, 2020). "These experimental results indicated a potential use of the d-Nav insulin guidance system for stable blood sugar control and the optimization of insulin management in type 2 diabetes patients." (PMID 32548087, 2020). "Lipid overflow, particularly of saturated free fatty acids, contributes to the pathophysiology of Type 2 Diabetes (T2D) by reducing insulin sensitivity and enhancing inflammation and mitochondrial dysfunction." (PMID 33101053, 2020). "In conclusion, the Swedish health practitioners seem to prefer insulin management in patients with type 2 diabetes and dementia, while other more recent antidiabetic medications are used less frequently." (PMID 32741836, 2020). "In patients with type 2 diabetes, a marked reduction was seen in all outcome measures, despite a wide distribution of insulin levels." (PMID 32314253, 2020). "In the case of type 1 diabetes, the body is unable or inadequately produce insulin while in the case of type 2 diabetes, insulin is less prevalent in the bloodstream or less properly utilized." (PMID 32984558, 2020). "It has been shown to stimulate glucose uptake, improve glycemic control and insulin action, and decrease hyperglycemia in insulin-resistant states, including type 2 diabetes, via various signaling processes and molecular mechanisms." (PMID 32467736, 2020). "Briefly, plasma glucose concentrations increased with escalating oral glucose loads in individuals with type 2 diabetes due to impaired insulin secretion and incretin responses when compared to matched control individuals." (PMID 32987824, 2020). "Glucagon-like peptide-1 (GLP-1) from intestinal L-cells stimulates insulin secretion and reduces appetite after food ingestion, and it is the basis for drugs against type-2 diabetes and obesity." (PMID 32610134, 2020). "The present study revealed that consumption of SPs alleviated hyperglycemia by enhancing insulin sensitivity and glucose-stimulated insulin secretion in an Asian type 2 diabetic animal model." (PMID 31991596, 2020). "PubMed was queried to identify intervention studies reporting glucose and insulin concentrations after acute ingestion and/or intravenous infusion of AAs in healthy adults and those living with obesity and/or type 2 diabetes (T2DM)." (PMID 33096658, 2020). "PPARγ agonists such as rosiglitazone are used as insulin-sensitizing agents to treat type 2 diabetes." (PMID 33776749, 2020). "Insulin is essential in the treatment of type 1 diabetes, and a key component in the treatment of the more common type 2 diabetes patient." (PMID 33202992, 2020). "This favors insulin treatment only in the late phases of type 2 diabetes as has been suggested in recent guidelines." (PMID 32819363, 2020). "A recent study observed that CD163 is inversely associated with insulin sensitivity and beta-cell function at OGTT and the risk of dysglycemia in adults at risk for type 2 diabetes." (PMID 32695161, 2020).